ITGA2 (integrin subunit alpha 2)
Diseases named in the same sentence as ITGA2 in open-access papers (continued):
Sharing a sentence is not in itself a finding about the gene and the disease.
triple-negative breast carcinoma (2 papers, 2022). An invasive breast carcinoma which is negative for expression of estrogen receptor (ER), progesterone receptor (PR), and human epidermal growth factor receptor 2 (HER2). "Moreover, ATP citrate lyase (ACLY), a key enzyme responsible for de novo fatty acid synthesis, was considered to enhance triple-negative breast cancer (TNBC) stemness and metastasis via miR-206/ITGA2/ACLY-CCND1 signaling axis." (PMID 35852149, 2022).
acral melanoma (1 paper, 2023). "Furthermore, ITGA2 has been found to be associated with the progression of acral melanoma and the clinical prognosis of patients suffering from the disease." (PMID 37881431, 2023).
acute coronary syndrome (1 paper, 2013). Signs and symptoms related to acute ischemia of the myocardium secondary to coronary artery disease. "An inverse association of the of ITGA2 rs28095 minor allele T with mean platelet volume in patients with acute coronary syndrome was observed, suggesting that α2 integrin plays a direct role in the regulation of mean platelet volume." (PMID 23359821, 2013).
Alport syndrome (1 paper, 2025). A rare renal disease characterized by glomerular nephropathy with hematuria progressing to end-stage renal disease (ESRD), frequently associated with sensorineural deafness, and occasionally with ocular anomalies. "Reduced ITGA2 expression may contribute to slower disease progression in heterozygous females, and the inhibition of collagen receptors may offer a novel strategy to treat patients with Alport syndrome." (PMID 40723524, 2025).
aneurysm (1 paper, 2021). Bulging or ballooning in an area of an artery secondary to arterial wall weakening. "This evidence supports that ITGA2 plays an essential role in the etiopathology of aortic diseases, including but not limited to aortic dissection and aneurysms." (PMID 35096998, 2021).
astrocytomas (1 paper, 2022). "The ITGA2 genotype +/+ (with a BglII restriction site in both alleles) exhibited higher frequency in grade II astrocytoma compared to control (P = 0.02) whereas the genotype -/- (lacking the BglII site) correlated with the poorest survival rate (P = 0.04)." (PMID 35936750, 2022). "Although the ITGA2 BglII +/+ polymorphism was overrepresented in grade II astrocytomas, it was associated with increased survival profile in this group." (PMID 35936750, 2022). "In addition, the increased frequency of the ITGA2 BglII polymorphism in grade II astrocytoma suggests a protective effect on the risk factor to LGG; however, more studies are necessary to correlate the polymorphism with tumor progression and overall survival." (PMID 35936750, 2022). "Our results indicate that BglII polymorphisms of ITGA2 have increased frequency in grade II astrocytoma cases and suggests a protective effect on the risk to LGG; however, more studies are necessary to correlate the polymorphism with tumor progression and overall survival." (PMID 35936750, 2022). "Our results revealed that the ITGA2 BglII +/+ genotype was significantly overexpressed in patients with grade II astrocytoma compared to controls, OR (95% CI) 4.38 (1.31–14.72) and P = 0.02." (PMID 35936750, 2022). "In contrast, male patients with astrocytoma showed higher frequencies than women for the ITGA2 BglII +/+ and +/- genotypes; however, these differences were not statistically significant." (PMID 35936750, 2022). "Regarding grade II astrocytoma, the ITGA2 genotype (+/+ and +/-) exhibited higher frequency and, in contrast, increased median survival compared to the homozygous -/- genotype." (PMID 35936750, 2022). "The total distribution of ITGA2 BglII genotypes was not significantly different between astrocytomas and controls." (PMID 35936750, 2022). "However, the distribution of integrin ITGA2 BglII genotypes (+/+, +/-, -/-) was not significantly different between astrocytoma subgroups III and IV (P = 0.65, 0.24 and 0.33; 0.29, 0.48, 0.25, respectively) compared to control." (PMID 35936750, 2022). "The correlation between overall survival and ITGA2 expression was not statistically significant to grade III and IV of astrocytomas." (PMID 35936750, 2022).
bladder cancer (1 paper, 2021). "Finally, the pathogenic roles of ITGA2 in bladder cancer cells should also be further explored using cellular and animal models." (PMID 34332611, 2021). "Moreover, miR-146b-5p suppressed ITGA2 expression in bladder cancer cells through direct association." (PMID 34332611, 2021). "To further clarify the relationship between miR-146b-5p and ITGA2 in bladder cancer cells, we then overexpressed miR-146b-5p in bladder cancer cells by transfection with miR-146b-5p mimics." (PMID 34332611, 2021). "lnc-STYK1-2 inhibited bladder cancer cell proliferation, migration, and tumorigenesis by targeting miR-146b-5p to regulate ITGA2 expression and AKT/STAT3/NF-kB signaling." (PMID 34332611, 2021). "lnc-STYK1-2 siRNA promoted miR-146b-5p and reduced ITGA2 expression in bladder cancer cells." (PMID 34332611, 2021). "For more understanding of the molecular mechanisms downstream of lnc-STYK1-2 and miR-146b-5p, we analyzed the influence of lnc-STYK1-2 and its suppression of miR-146b-5p on the expression of ITGA2 and AKT/NFκB/STAT3 axis activation in bladder cancer cells." (PMID 34332611, 2021). "Together, these results revealed that ITGA2 and AKT/NFκB/STAT3 signaling pathways were regulated by lnc-STYK1-2 and miR-146b-5p in bladder cancer cells." (PMID 34332611, 2021). "Also, ITGA2 expression and phosphorylation of AKT, STAT3, and p65 proteins in bladder cancer cells were greatly enhanced by silencing of lnc-STYK1-2 expression." (PMID 34332611, 2021).
bleeding disorders (1 paper, 2023). "Dysregulation of ITGA2 contributes to bleeding disorders, cancer metastasis, fibrosis, and inflammatory conditions." (PMID 38107572, 2023).
Hepatic fibrosis (1 paper, 2025). The presence of excessive fibrous connective tissue in the liver. "Classical fibrotic mediators and markers (including Tgfb1, Timp1, and Vcam1), collagen of the ECM (including Col4a1, Col4a2, Col16A1, and Col18a1) and cell surface adhesion and signaling integrin (Itga2, Itga5) were found to be differentially expressed in the enriched hepatic fibrosis pathways." (PMID 39747668, 2025).
mammary adenocarcinoma (1 paper, 2023). "Specifically, ITGA2 is a known target of miR-20a and miR-15b, therefore representing an interesting panel of molecular targets warranting further investigation in felines with mammary adenocarcinoma." (PMID 37280313, 2023).
memory impairment (1 paper, 2024). "Overall, these findings suggest that DG S1PR1 may govern the susceptibility of memory impairment by regulating actin polymerization via interaction with ITGA2." (PMID 39699949, 2024).
metastatic cancer (1 paper, 2015). A carcinoma which has spread from the original site of growth to another anatomic site. "Furthermore, the metastatic cancer cells MDA-MB-231 were co-transfected with anti-miR-373 and siRNA-targeted ITGA2." (PMID 26258411, 2015).
oligodendroglioma (1 paper, 2022). A well-differentiated (WHO grade II), diffusely infiltrating neuroglial tumor, typically located in the cerebral hemispheres. "The analyses demonstrated that, in LGG, oligodendrogliomas were associated with low ITGA2 expression as well as lower-grade tumors (Grade 2)." (PMID 35936750, 2022).
Pleural effusion (1 paper, 2021). The presence of an excessive amount of fluid in the pleural cavity. "GNG12 and ITGA2 have been reported to relate to T/NK cells in pleural effusion." (PMID 34575089, 2021).
renal fibrosis (1 paper, 2017). A final common manifestation of a wide variety of chronic kidney diseases characterized by glomerulosclerosis and tubulointerstitial fibrosis. "The COL4A3−/−/ITGA2−/− double knockout Alport mouse model has delayed renal fibrosis compared with COL4A3−/−/ITGA2+/+ Alport mice, which express significantly higher levels of MMP2, MMP9, MMP12, and TIMP155." (PMID 29196624, 2017).
serous ovarian cystadenocarcinomas (1 paper, 2022). "Amongst the proteomics identified and validated genes, the expression of TGFBI significantly positively correlated with the expression of GFPT2, FLNA, G6PD, ITGAV, ITGA1 and ITGA2 within the serous ovarian cystadenocarcinomas in TIMER database." (PMID 36463238, 2022).
skin tumors (1 paper, 2025). "Further, we found activated NK cells in skin tumors indicated by higher levels of NK activation genes including Gzmb, Gzma, Eomes, Itga2 (Cd49b), and Klra8." (PMID 40282557, 2025).
Thromboembolism (1 paper, 2025). The formation of a blood clot inside a blood vessel that subsequently travels through the blood stream from the site where it formed to another location in the body, generally leading to vascular occlusion at the distant site. "The study indicates that patients with the T/T genotype of ITGA2 and ITGB3 may have an elevated risk of thromboembolism." (PMID 41346645, 2025).
thyroid tumor (1 paper, 2018). A benign or malignant neoplasm affecting the thyroid gland. "In this study, we recruited a cohort of patients with PTC and determined the levels of ITGA2, SYT12 and CDH3 mRNA in resected thyroid tumors." (PMID 29255621, 2018).
Uterine leiomyoma (1 paper, 2023). The presence of a leiomyoma of the uterus. "The results of ChIP-seq and RNA-seq confirmed that BPA promoted the proliferation of uterine leiomyoma cells by acting on X-box binding protein 1 (XBP1) and downstream integrin subunit alpha 2 (ITGA2), thereby activating the PI3K/AKT signaling pathway." (PMID 38133401, 2023).
tumor (251 papers, 1998 to 2026). "Similar association was observed for PCa tumor with ITGA2 copy number loss/del (P = 1.26e‐05, ln(HR) = 0.77; 95% ln(CI): 0.42– 1.11)." (PMID 38169150, 2024). "Early studies have shown that ITGA2 is overexpressed in a variety of tumors and is closely associated with tumor cell proliferation, migration, and invasion." (PMID 39199378, 2024). "Herein, a meta‐analysis of multiple PCa cohorts is performed which revealed that downregulation or genomic loss of ITGA1 and ITGA2 integrin genes is associated with tumor progression and worse prognosis." (PMID 38169150, 2024). "In other studies, ITGA2 was highly expressed in PDAC tumor tissue, and ITGA2 expression was significantly associated with gemcitabine resistance and poor prognoses in PDAC patients." (PMID 37377917, 2023). "The subunit of integrin ITGA2 was found to be upregulated in several types of cancer and has been associated with tumor cell proliferation, migration, invasion, and angiogenesis." (PMID 35936750, 2022). "Linear regression analysis indicated that while ITGA5 had positive correlation with Breslow thickness (as a continuous variant) ITGA2 was in strong significant inverse correlation with the Breslow thickness of the tumor." (PMID 36091936, 2022). "As a subunit of integrin, ITGA2 is closely associated with tumor cell proliferation, migration, and invasion." (PMID 31818309, 2019). "Excess expression of both Collagen (COL11A1, COL7A1) and Integrin (ITGA2) is known to be associated with cell invasiveness and tumor formation." (PMID 28821810, 2017). "Under normal cell differentiation, expression of ITGA2 is regulated and kept within normal range but its over-expression is associated with decreased tumor cells motility and invasiveness." (PMID 29121049, 2017). "Furthermore, silencing ITGA2 abrogates the promotion of tumor cell migration, invasion, and adhesion caused by PSAT1 overexpression." (PMID 39199378, 2024). "Indeed, previous studies demonstrate that ITGA2/B1 is primarily a receptor for collagen and laminin and expression is also associated with motility, invasiveness, and cellular differentiation of a variety of tumours." (PMID 33276802, 2020). "Moreover, integrin alpha 2 (ITGA2) is associated with caveolin-1 in tumor cells." (PMID 21209926, 2010). "In vivo experiments indicated that ITGA2 overexpression promotes tumor growth in transplantation, whereas its knockdown inhibits tumor progression." (PMID 40940943, 2025). "Functional validation using antibody blockade in patient‐derived organoid models recapitulated ITGA2's tumor‐promotive effects, though conserved oncogenic mechanisms between pediatric and adult cohorts warrant further exploration." (PMID 40985182, 2025). "The tumor microenvironment (TME) analysis uncovered ITGA2's emerging role as a mediator of immune‐stromal crosstalk." (PMID 40985182, 2025). "The Western blotting results indicated that the expression level of ITGA2 in the tumor tissue of the combined treatment group was lower than that in the control group." (PMID 40940943, 2025). "The integrin ITGA2, which mediates adhesion and signaling, increases tumor aggressiveness when overexpressed, while its inhibition increases radiosensitivity." (PMID 41304780, 2025). "ITGA2hi‐PTC cells were increased in PPTC samples and exhibited high expression of ITGA2, KRT6A, SOSTDC1, KRT6B, and KRT14, genes associated with tumor progression." (PMID 40985182, 2025). "Tumor sphere formation assays, flow cytometry analyses, and in vivo limiting dilution tumorigenicity evaluations demonstrated that knocking down ITGA2 significantly impaired stemness." (PMID 40316546, 2025). "To validate the observed accumulation of integrins on the tumor cell surface, we focused on the most enriched integrins upon AP2 loss, namely ITGB1, ITGB6, ITGA2, and ITGA3." (PMID 40050266, 2025). "Variations in ITGA2 expression subtly and dynamically influence the tumor immune microenvironment and immunogenicity." (PMID 40332099, 2025).
tumor (continued). "The diverse mechanisms through which ITGA2 facilitates communication between CAFs and tumor cells highlight the importance of investigating the functional alterations of ITGA2 in the TME." (PMID 39568561, 2024). "An increasing body of evidence suggests that the interaction between ITGA2 and collagen facilitates the migration and metastasis of tumor cells." (PMID 39568561, 2024). "For ITGA2, a positive correlation between its expression and methylation was observed, in line with both lower expression and methylation level in tumor vs. normal tissues in PRAD." (PMID 39436262, 2024). "Recent research findings indicate that targeting ITGA2 leads to an augmentation in the population of tumor-killing lymphocytes, while concurrently reducing the proportion of immunosuppressive cells within the tumor." (PMID 39568561, 2024). "Recent investigations have revealed that tumor-infiltrating CD8+T cells initially exhibit ITGA2 expression, which subsequently facilitates the repositioning of T cells within the TME and induces CD8+T cell dysfunction." (PMID 39568561, 2024). "Integrin α2 (ITGA2) is highly expressed in various cancers, and its upregulation promotes tumor proliferation, invasion, migration, and angiogenesis." (PMID 39684926, 2024). "In the context of digestive cancers, the primary role of ITGA2 lies in the regulation of tumor cell’s malignant biological behavior, subsequently influencing the progression, metastasis, and resistance to chemotherapy." (PMID 39568561, 2024). "The crucial role of ITGA2 in tumor progression and its correlation with clinical factors prompted us to conduct further investigations." (PMID 37386391, 2023). "Integrin alpha 2 (ITGA2) is a trans-membrane receptor that facilitates cell adherence to the ECM that is deregulated in various tumor types." (PMID 36740668, 2023). "Our analysis revealed a positive correlation between ITGA2, E-cad and PD-L1 in both the tumor and stroma." (PMID 37881431, 2023). "Studies have demonstrated the critical role of ITGA2 in tumor metastasis, invasion and angiogenesis." (PMID 37386391, 2023). "Among the genes exhibiting high expression in different tumor tissues, ITGA2 stands out as a promising candidate for cancer therapy." (PMID 37881431, 2023). "Further research is needed to explore the connection between ITGA2 and Treg cells in promoting the formation of an immunosuppressive microenvironment, as well as their role in tumor development." (PMID 37881431, 2023). "LINC00355 was shown to promote cancer cell proliferation and tumor growth in xenograft animals by regulating the transcription of three genes (ITGA2, RAD18, and UBE3C) and participating in seven ceRNA axes." (PMID 38125763, 2023). "Our findings suggest indicate a significant correlation between ITGA2+ cells in the tumor area and E-cadherin+ (r=0.599, P< 0.001) and PD-L1+ (r =0.511, P <0.001)." (PMID 37881431, 2023). "More precisely, inhibition of ITGA2 would alleviate tumor solid stress, block cancer cell aberrant proliferation, and partially prevent chemoresistance." (PMID 36765586, 2023). "Then, sphere formation demonstrated that the capacity of spheres formation of tumor cells obviously increased in co-cultured with TAFs group, and were markedly reduced after knocking down ITGA2." (PMID 35322024, 2022). "ITGA2 was highly expressed in the spots adjacent to the tumor stroma expressing COL3A1 of post-treatment tumors." (PMID 36505794, 2022). "Intrigued by the pivotal roles of integrins in the intercellular network, we sought to choose the most significant tumor cell–expressed integrin, ITGA2, for protein expression and druggable potential testing." (PMID 35719923, 2022). "The scRNA-seq data showed that ITGA2 was mainly expressed in tumor cells, while its ligands COL1A1, COL1A2, COL8A1, FN1, and HSPG2 were expressed in fibroblasts and endothelial cells." (PMID 35719923, 2022).